IGF1 (insulin like growth factor 1)
Diseases named in the same sentence as IGF1 in open-access papers (continued):
Sharing a sentence is not in itself a finding about the gene and the disease.
cancer (continued). "Genetic polymorphisms of IGF-1 may also increase the risk of cancer." (PMID 23304125, 2012). "However, aberrations of this molecular pathway such as overexpression of IGF1R, elevated plasma levels of IGF1, loss of IGF2 imprinting, or genetic polymorphisms of the gene encoding IGF1 have been found in many cancers, affecting multiple aspects of malignancy such as tumor growth and metastases." (PMID 21078151, 2010). "Losartan also directly suppresses insulin-like growth factor-1 (IGF-1) signaling within cancer cells." (PMID 41596584, 2026). "Inhibition of IGF1R in this context reduces residual disease burden and cancer recurrence, underscoring the broader relevance of IGF1 signaling in KRAS driven cancer." (PMID 41526435, 2026). "We demonstrated that the anti-cancer efficacy of 2B7 is mediated by the inhibition of the IGF1/IGF1Rβ and OPN/CD44 signaling, both central to cancer stem cell regulation, and by suppressing immune evasion via downregulation of PD-L1 and B7-H4." (PMID 41356204, 2026). "IGF-1 and IGF-2 secreted by tumor-associated macrophages and myofibroblasts contribute to chemoresistance in PaC by activating insulin/IGF receptors on cancer cells." (PMID 41583513, 2026). "Chronic IGF‐1 signaling exacerbates tumor progression by supporting cancer cell metabolism and therapy resistance." (PMID 40387523, 2025). "Beyond developmental functions, circulating IGF-1 levels correlate with musculoskeletal performance and show altered regulation across various chronic diseases including cancer and metabolic disorders." (PMID 41586110, 2025). "These pathways, including the IGF-1 system, adipokine signaling, and the distribution of sex hormones, create a favorable environment for cancer initiation and progression." (PMID 40034825, 2025). "blood glucose and IGF-1 levels, induces apoptosis and oxidative stress, kills tumour cells while sparing normal cells, and enhances tolerance to cancer therapy." (PMID 41335382, 2025). "Our findings align with previous research indicating that IGF1 signaling governs mitochondrial dynamics and turnover in cancer cells through the NRF2‐BNIP3 pathway." (PMID 40294065, 2025). "In cancer, the IGF-1 pathway plays a crucial role in creating an environment conducive to tumor development by driving cell division and inhibiting apoptosis." (PMID 39940361, 2025). "The aim of this review was to identify and characterize the miRNA-induced regulation of the IGF-1 system in various types of cancer." (PMID 41153350, 2025). "Insulin and insulin‐like growth factor‐1 (IGF‐1), which are elevated in obese individuals, act as potent mitogens and survival factors for cancer cells, stimulating proliferation, inhibiting apoptosis, and enhancing tumor cell migration and invasion." (PMID 39969135, 2025). "IGF-1 is a potent promoter of cell proliferation and an inhibitor of apoptosis, making it a potential mediator of cancer development, including lymphomas." (PMID 41374067, 2025). "It is believed to alleviate some symptoms of cancer cachexia by inhibiting MuRF‐1/MAFbx‐induced protein degradation in muscle tissue, promoting muscle protein synthesis via IGF‐1, and increasing fat accumulation." (PMID 39764565, 2025). "Elevated glucose levels enhance tumour metabolism and DNA damage, while hyperinsulinaemia and insulin‐like growth factor‐1 (IGF‐1) stimulate cancer cell proliferation." (PMID 40998759, 2025). "By reducing circulating glucose and insulin levels, KD suppresses the insulin/IGF-1 signaling axis, a key driver of cancer cell proliferation and survival." (PMID 40428567, 2025). "For instance, cathepsin G induces cell migration, activates insulin-like growth factor 1 (IGF-1), increases E-cadherin-mediated intercellular adhesion and cancer cell aggregation, and promotes the entry of cancer cells into blood vessels." (PMID 40342932, 2025).
cancer (continued). "This link is thought to be due to elevated levels of growth factors and hormones, such as insulin-like growth factor 1 (IGF-1), which play a role in cancer development." (PMID 40989682, 2025). "Clinical studies have shown that exercise not only significantly reduces adverse conditions related to tumor prognosis, such as cardiotoxicity, but also improves the body composition of cancer patients, including insulin-like growth factor-1." (PMID 40704062, 2025). "The tumour microenvironment (TME), particularly hypoxia, significantly influences IGF1 signalling, posing challenges in cancer therapy." (PMID 39796756, 2025). "By activating AMPK and reducing insulin and IGF-1 signaling, metformin mirrors some of the cancer-protective effects of CR, promoting cellular resilience and reducing cancer-promoting pathways." (PMID 39940361, 2025). "A critical mechanism through which FMD exerts its anti-cancer effects is the reduction in circulating IGF-1." (PMID 39940361, 2025). "Ginsenoside F1 enhances NK cell cytotoxicity through IGF-1-dependent mechanisms, promoting cancer surveillance in mouse models of lymphoma clearance and metastatic melanoma." (PMID 41155644, 2025). "GH induces the production of >75% of circulating IGF1, which in turn is a well-studied oncogenic factor across cancer types." (PMID 41515995, 2025). "An increase in insulin or IGF-1 levels, commonly seen in T2DM, is strongly associated with increased cancer risk and mortality." (PMID 40764810, 2025). "In this cancer, Klotho modulates the IGF-1 and FGF pathways, reducing tumor cell proliferation and enhancing apoptosis." (PMID 40004457, 2025). "Insulin and insulin-like growth factor-1 (IGF-1) signaling pathways also play a crucial role in cancer development as their overactivation can promote cell proliferation and survival." (PMID 40428567, 2025). "IGF1-Ec is believed to play a mitogenic role in tumours, supported by research on human cancer cell lines." (PMID 39796756, 2025). "The IGF1 pathway interacts with genetic and environmental factors known to contribute to cancer development." (PMID 40659611, 2025). "Additional miRNAs and their role in IGF-1’s effects on other types of cancer have also been identified." (PMID 41153350, 2025). "The heightened expression of insulin-like growth factor 1 (IGF-1) in ECs within the tumor vascular niche induces elevated expression of the IGF-1 receptor in adjacent cancer cells." (PMID 40821116, 2025). "This study demonstrated that the ESCC cells with high expression of QSOX2 were mainly located near the edge of the cancer nest, which was regulated by IGF‐1 secreted by CAFs." (PMID 40433832, 2025). "One study demonstrated that the inhibition of IGF-1 signaling reduced Akt and Erk phosphorylation and thus slowed cancer proliferation, though this was correlative." (PMID 40722609, 2025). "Of the iCAF signature expressing subsets specific to cancers, IGF1 + CAF and IL11 + CAF were abundant in tumours." (PMID 39757146, 2025). "The identification of IGF1 as a mediator in the telomere–CRC pathway provides crucial mechanistic insights that align with established cancer biology principles." (PMID 41444654, 2025). "Metformin exerts anti‐cancer effects by suppressing IGF‐1 and insulin signaling pathways, which are key regulators of cell growth, metabolism, and tumor progression." (PMID 40387523, 2025). "Research has shown that this dietary intervention reduces insulin-like growth factor-1 (IGF-1) and increases ketone body production, with studies in animal models demonstrating that limiting carbohydrate intake can impede cancer progression." (PMID 41398969, 2025). "Another mechanism highlighting the importance of regular physical activity is the lowering of IGF1 levels, which helps regulate cell growth and prevents cancer progression." (PMID 40507982, 2025).
cancer (continued). "It has been proposed that dysfunctional WAT contributes to the pathophysiology of cancer by raising systemic levels of leptin, steroid hormones, insulin, and insulin‐like growth factor‐1 (IGF‐1) while lowering the concentration of adiponectin." (PMID 39496581, 2025). "A pilot clinical trial, performed on healthy adults, showed it to be feasible, without any major adverse effects, and able to decrease some biomarkers for cancer, namely, reducing fasting blood glucose levels and circulating IGF-1." (PMID 39940361, 2025). "CR-mediated IGF-1 reduction also suppresses inflammation, another key contributor to cancer progression, by reducing the activation of pro-inflammatory pathways like NF-κB, which are often stimulated by IGF-1 signaling." (PMID 39940361, 2025). "Despite extensive exploration of IGF1R inhibitors and IGF1-targeting strategies in cancer therapy, their clinical efficacy has been limited in inhibiting tumor progression." (PMID 41515995, 2025). "IGF-1 is a known promoter of the growth of cancer cells, including lymphocytes, which provide the starting point for tumor transformation in HL." (PMID 41374067, 2025). "Several studies reported elevated GH and IGF-1 levels at any cancer diagnosis, but methodological heterogeneity limited conclusions on dose–response or temporal associations." (PMID 41293738, 2025). "A recent study identifies a hypoxia induced senescent cancer associated fibroblast (hsCAF) subpopulation that promotes ESCC stemness and chemoresistance via IGF1 signaling, highlighting hsCAFs as a potential therapeutic target." (PMID 41476608, 2025). "In conclusion, insulin and IGF-1 signaling pathways are critical drivers of cancer development and progression, and their dysregulation is strongly influenced by diet and nutrition." (PMID 40428567, 2025). "Individuals with acromegaly (excess GH and IGF-1) have an increased incidence of cancers, while individuals with Laron Syndrome (congenital GH insensitivity due to non-functional GHR) are remarkably almost completely resistant to all cancers." (PMID 41515995, 2025). "The PI3K/AKT pathway, a key mediator of insulin and IGF‐1 signaling, promotes glycolysis and lipid biosynthesis, which are crucial for rapidly dividing cancer cells." (PMID 40387523, 2025). "IGF1 has been reported to mark iCAF in several cancer types, and this low activation subset probably represents the most commonly referenced ‘iCAF’ phenotype in the literature currently." (PMID 39757146, 2025). "Among 15 ginsenosides evaluated, F1 showed the most robust enhancement of NK cell cytotoxicity against diverse cancer cell types via an IGF-1 dependent mechanism." (PMID 41155644, 2025). "Recent research has focused on understanding the role of specific IGF1 isoforms in cancer biology, yet their involvement in the development of EC remains inconclusive." (PMID 39796756, 2025). "This dual suppression of IGF‐1 and insulin signaling is a key mechanism by which metformin exerts its anti‐tumorigenic effects across various cancers." (PMID 40387523, 2025). "The IGF1 signalling pathway is a vital modulator of cancer progression, including EC, rendering it a compelling therapeutic target." (PMID 39796756, 2025). "Within the HNSCC dataset, ~ 50% of PI16 labelled fibroblasts from tumour samples were labelled as IGF1 + CAF in the pan-cancer analysis, suggesting that this phenotype is an early/low activation phenotype consistent with previous studies." (PMID 39757146, 2025). "Endocrine GH action directly regulates the levels of another hormone called insulin-like growth factor 1 (IGF1), which is a well-established target in cancer." (PMID 41515995, 2025).
cancer (continued). "IGF1 + CAF were present in most cancer types (e.g., breast, oesophageal, lung), including high levels in PDAC (where they were comparable to myCAF in abundance)." (PMID 39757146, 2025). "IGF-1 enhances platelet activation through the IGF receptor/IRS/PI3K/PKB pathway, contributing to cancer-associated hypercoagulability and metastasis." (PMID 41226816, 2025). "Evidence from human and animal studies indicates that exercise-induced weight loss reduces circulating levels of IGF-1, insulin, and leptin, thereby downregulating IGF-1-related pathways and promoting cell cycle arrest and cancer suppression." (PMID 40731797, 2025). "Hyperinsulinemia resulting from insulin resistance and subsequent hyperglycemia promotes cancer development by raising circulating levels of free IGF‐1 and IGF‐2, as reported in OC." (PMID 39969135, 2025). "IGF1, ubiquitously expressed with complex metabolic regulatory roles, has emerged as a promising therapeutic target for cancer." (PMID 39796756, 2025). "One study reported that certain cancers are stimulated by IGF-1 or IGF-2 through endocrine, autocrine, or paracrine mechanisms." (PMID 40004457, 2025). "After screening, 24 studies (>17,000 patients) were included, with data on cancer frequency, timing, and GH/IGF-1 levels extracted for analysis." (PMID 41293738, 2025). "Evidence from other cancers further underscores the relevance of IGF1 isoforms in driving tumour behaviours, offering valuable insights into their potential as biomarkers and therapeutic targets." (PMID 39796756, 2025). "Increased insulin-like growth factor 1 signaling can potently blunt chemotherapy response, and lysosomal processes including the nutrient scavenging pathway autophagy can enable cancer cells to evade chemotherapy-mediated cell death." (PMID 38786030, 2024). "The activation of the EGFR signaling pathway enhances IGF-1 secretion and directly drives M2 macrophage polarization, resulting in an immunosuppressor effect and promoting the development of cancer." (PMID 39619695, 2024). "In cancer, the IGF1/IGF1R axis appears to play a role in modulating DC activity toward an immature state with immunosuppressive and tumor-promoting activities." (PMID 38420122, 2024). "The relationship between elevated levels of IGF1 and cancer is well established, elucidating higher cancer rates in obese individuals." (PMID 38255007, 2024). "For instance, high serum IGF-1 and IGFBP-3 levels raise the risk of numerous cancers; however, in a meta-analysis, IGFBP-3 decreased the risk of lung cancer." (PMID 38928185, 2024). "While there has been extensive research on the role of insulin-like growth factor 1 (IGF1) in various cancers, investigations into the potential impact of insulin itself have been relatively limited." (PMID 38339407, 2024). "Long-term chronic inflammation and increased IGF-1/Insulin production can lead to cancer progression." (PMID 38339407, 2024). "Receptors for insulin and IGF-1 are expressed in most cancer cells, and receptor activation results in signaling pathways capable of stimulating cancer cell proliferation, protection from apoptotic stimuli, invasion and metastasis." (PMID 37347429, 2024). "The Figure summarizes the way insulin and IGF-1 affect cell metabolism and possible cancer development." (PMID 38339407, 2024). "This increase in insulin promotes the activity of IGF-1, which also promotes cancer cell proliferation by inhibiting apoptosis." (PMID 40046187, 2024). "Conversely, individuals with elevated growth hormone/IGF-1 signaling, such as those with acromegaly, have increased cardiovascular and cancer risks." (PMID 39200386, 2024). "It is well understood that in the liver, the binding of GH to GH receptors leads to the production of IGF-1, which is also known to be a potent mitogenic factor and contributes to the growth of a plethora of cell types, cancers included." (PMID 39417961, 2024).
cancer (continued). "The insulin-like growth factor 1 receptor (IGF-1R) and its ligands (IGF-1 and IGF-2) are essential for cell, organ, and organismal growth, and are linked to cancer risk, cancer progression, and inflammation." (PMID 39608716, 2024). "IGF1R attenuation is achievable by IGF1R inhibitors, and IGF1 is deemed a provocative target in anti-cancer research, supported by a plethora of studies." (PMID 39000545, 2024). "Systemically, GH action drives insulin resistance and, again, IGF1 production, both of which are detrimental factors in cancer prognosis." (PMID 39000545, 2024). "The IGF-1 signaling system can stimulate cancer progress by preventing apoptosis and stimulating cell proliferation." (PMID 38500219, 2024). "FMD has been developed as a low-calorie, low-protein strategy to mimic the fasting state, which has been reported reduce plasma levels of insulin-like growth factor 1 (IGF-1), insulin, and glucose as mediators of cancer cell growth and progression." (PMID 39703333, 2024). "In vitro experiments demonstrated that the addition of IGF-1 promotes the growth of PDAC cancer cell lines." (PMID 39638246, 2024). "Analogously, some cancers are also vulnerable to ferroptosis and emerging studies have identified local IGF1 as a supportive factor for the maintenance of cancer stem cells." (PMID 38802843, 2024). "IGF-1 stimulates most steps of cancer progression by signaling through the IGF-1 receptor (IGF-1R), and IGF-2 promotes tumor growth through binding primarily to the insulin receptor subtype A (IR-A)." (PMID 38396692, 2024). "Highlighting the significance of interactions with extracellular growth factors such as VEGFA and IGF1 in cancer growth and progression, several targets, including CCND1, WEE1, VEGFA, and CDK6, were identified to interact with two miRNAs." (PMID 39614097, 2024). "During periods of fasting, there is a decrease in the levels of IGF-1 and insulin, which are growth factors that support the growth and survival of cancer cells." (PMID 39310400, 2024). "This time frame encompasses significant advancements in the field, capturing the latest insights into IGF-1 signaling mechanisms and their implications in cancer biology." (PMID 39273251, 2024). "Functionally speaking, IGF1-polarized TAMs promoted in vitro migration and proliferation of cancer cells." (PMID 38892104, 2024). "IGF1 signaling has been demonstrated to play a crucial role in the development and progression of cancers, including ovarian." (PMID 39450263, 2024). "The study of GRAs in cancer anorexia-cachexia syndrome is interesting due to their propensity to stimulate hunger, the increase in IGF-1 observed with GRAs, and the role of IGF-1 in maintaining or hypertrophying muscle mass in dogs." (PMID 39434876, 2024). "As such, the potential therapeutic application of IGF-1 in the treatment of cancer cachexia should also be considered." (PMID 38334644, 2024). "KD reduces blood glucose and lowers insulin and IGF-1 activity and provides a metabolic strategy to potentially slow cancer cell expansion." (PMID 39534224, 2024). "Despite extensive research, the precise molecular pathways and intracellular mechanisms activated by IGF-1, in cancer, remain poorly understood." (PMID 39273251, 2024). "Treatment modalities targeting IGF-1 are potential strategies for cancer therapy, and the observed effects of E4 in the PCombi study suggest a favorable effect on IGF-1." (PMID 39408055, 2024). "Several monoclonal antibodies targeting IGF1R or IGF1 proteins have been tested in the clinic for different diseases, including cancer." (PMID 38420122, 2024). "Linsitinib inhibition of the IGF-1 signaling pathway is a promising therapeutic option to treat OC patients, demonstrating significant anti-cancer effects in in vitro assays." (PMID 39596005, 2024). "Enhanced insulin sensitivity helps modulate the insulin and insulin-like growth factor-1 (IGF-1) pathways, which are implicated in the progression of several cancers." (PMID 38831183, 2024).